APAF1 (apoptotic peptidase activating factor 1)
Diseases named in the same sentence as APAF1 in open-access papers (continued):
Sharing a sentence is not in itself a finding about the gene and the disease.
cancer (137 papers, 2002 to 2025). A tumor composed of atypical neoplastic, often pleomorphic cells that invade other tissues. "First, RTA dh404 promoted or inhibited genes associated with cancer cell apoptosis, including three genes (Apaf-1, Bcl-2, and BCL-XL) in GBM8401 cells and three genes (NOXA, BCL-XL, and FADD) in U87MG cells." (PMID 36835414, 2023). "Our data reported that HSA caused to increase the expression of proapoptotic protein Apaf-1 at serum as well as at cancer tissues level." (PMID 35386216, 2022). "Many of the EP/EN events are previously reported and experimentally validated to be alternatively spliced in various diseases including cancer, For instance, APAF1 gene encodes an apoptotic protein and hosts an EN exon encoding WD40 domain in developing brain." (PMID 36509773, 2022). "For example, binding of cancer-associated fibroblast (CAF)-derived exosome miR-21 to APAF1 in ovarian cancer cells confers paclitaxel resistance to cancer cells." (PMID 35880180, 2022). "Further, miR-21 is secreted via EVs from cancer-associated adipocytes and CAFs, leading to inhibition of APAF1 in recipient cells of the TME." (PMID 32957712, 2020). "Exosomes secreted from cancer-associated adipose cells or CAFs transfer miR-21 into cancer cells, thereby increasing the apoptotic threshold of paclitaxel treated OC cells via down-regulating expression of apoptotic protease-activating factor-1 (APAF1)." (PMID 35662846, 2022). "In ovarian neoplasm, miRNA 21 derived from CAFs and cancer associated adipocytes was transferred to cancer cells, which conferred paclitaxel resistance by directly targeting apoptotic protease activating factor-1(APAF1)." (PMID 34095111, 2021). "APAF1 is implicated in many pathways such as apoptosis, neurodegenerative diseases, and cancer." (PMID 31892812, 2019). "The up-regulated TNF-β, TNFRSFs (tumor necrosis factor receptor superfamily members) and Cytochrom C (Cyto C) in apoptosis antibody array implied that the cancer cell apoptosis was triggered by death receptors and transduced from a Cyto C/Apaf-1/Caspase-9 to Caspase-3 pathway linked to mitochondria." (PMID 27464624, 2016). "The Apaf-1 protein binds and cleaves caspase-9 preproprotein, releasing the mature, activated caspase-9, which stimulates a subsequent caspase cascade that causes the cancer cell to undergo apoptosis." (PMID 25624917, 2015). "It has been well-evidenced that apoptosis-resistant cancer cells die slowly in response to DNA damage when apoptosis downstream events are blocked by expression of oncogenic Ras, Raf, mitogen-activated kinases and apoptosis inhibitor Smac/Diablo, or deficiency of Apaf-1." (PMID 26093086, 2015). "In addition in some cancers a defective Cyt-C dependent caspase 9 activation in the presence of normal or elevated Apaf1 levels has been reported but the underlying molecular mechanism is still elusive and the existence of an unidentified apoptosome inhibitor has been suggested." (PMID 22683550, 2012). "Many studies have reported that in various malignant tumors, activated Apaf-1 can increase the sensitivity of chemotherapy drugs and promote apoptosis of tumor cells." (PMID 40426921, 2025). "K-means clustering of >600 000 cancer cells and cell level intensities of APAF1, procaspase-9, procaspase-3, XIAP, SMAC, BAX, BAK, BCL2, BCL-XL, MCL-1, procaspase-8, BID, FADD, FLIP, RIP3 and CIAP1 identified distinct cell cluster profiles." (PMID 39886119, 2024). "The decrease of APAF1 expression following DNA methylation or deactivation of the protein is common in different cancer types." (PMID 39598439, 2024). "TRIAP1 is highly expressed in MM,371 and overexpressed TRIAP1 can inhibit the activation of APAF1/apoptosome, thereby inhibiting cancer cell apoptosis, leading to cancer progression." (PMID 37256211, 2023). "Increased APAF1 expression is well-described in many types of cancer exposed to chemotherapeutic drugs." (PMID 38283944, 2023).
cancer (continued). "In OC, overexpressed TRIAP1 inhibits apoptosis of cancer cell SKOV3 by inhibiting the activation of APAF1/apoptosome." (PMID 37256211, 2023). "When TRIAP1 is overexpressed, it can impede the activation of APAF1/apoptosome, consequently blocking apoptosis in cancer cells." (PMID 38003971, 2023). "Our results suggest that miR21 can metastasize from CAAs or CAFs to cancer cells and then inhibit ovarian cancer cell apoptosis and enable cancer cells to acquire drug resistance by binding to APAF1." (PMID 36465402, 2022). "In OC, paclitaxel-resistant CAFs transfer miR-21 containing EVs to cancer cells targeting APAF1 and apoptosis, thereby promoting therapy resistance." (PMID 35646668, 2022). "In three cancer cell lines, mRNA levels of Bcl2, APAF1, and caspase-3 were evaluated at ascending concentrations and around IC50 concentrations by real-time-qPCR reported by fold change." (PMID 36204226, 2022). "M2 macrophages, DCs, and T cells derived exosomes carry large amounts of miR-21, which can induce drug resistance in cancer cells by binding to APAF1." (PMID 35550636, 2022). "Cyt-C interacts with apoptotic protease activating factor 1 (Apaf-1) proteins, which then activates caspase 9 to induce apoptosis in cancer cells." (PMID 35963853, 2022). "The intra-cytoplasmatic release of miR-21 in cancer cells downregulates the mRNA for apoptotic peptidase activating factor 1 (APAF-1)." (PMID 34440886, 2021). "In ovarian cancer, miR-21 is reportedly transferred from CAFs to cancer cells by exosomes, where it suppresses cancer cell apoptosis and confers paclitaxel resistance through targeting APAF1." (PMID 30642385, 2019). "Hsp70 would interfere with apoptosis by binding to APAF-1, inhibiting its oligomerization, and blocking apoptosome assembly, thereby increasing the probability of cancer cell survival." (PMID 31514388, 2019). "Experiment demonstrated the expression of multiple Apaf-1 isoforms in cancer cells, and specific isoform activate procaspase- 9 in response to cytochrome-c and dATP, and form apoptosomes." (PMID 29681851, 2018). "The majority of strong indirect interactions pointed to the 3 key apoptosis proteins CASP9, CASP3 and APAF1 (apoptotic protease activating factor) whose local PageRanks decreased in the “cancer” network (which means they become more regulated)." (PMID 29370181, 2018). "TH treatment groups were found to have a lower anti-apoptotic proteins (E2, ESR1 and Bcl-xL) expression and a higher pro-apoptotic proteins (Apaf-1 and Caspase-9) expression at serum and on cancer tissue level (p < 0.05)." (PMID 28399853, 2017). "The authors showed that miR21 was transferred by exosomes from CAAs or CAFs to cancer cells, where it suppressed ovarian cancer apoptosis and conferred chemoresistance to paclitaxel by binding to its direct target, APAF1." (PMID 28915700, 2017). "Previous studies have reported that TIIA can induce mitochondria-dependent apoptosis by regulating caspase-9 and Apaf-1 in several types of cancer." (PMID 25652794, 2015). "AMF can also down-regulate caspase-9 and Apaf-1, making cancer cells more resistant to mitochondria-dependent apoptosis." (PMID 25652794, 2015).
cancer (continued). "Because we observed Apaf-1 binding and truncation of TCTP in a single cell line following TCTP overexpression, other types of etoposide-resistant cancer cells need to be explored for verifying the Apaf-1-TCTP interaction." (PMID 24606760, 2014). "For example, numerous studies of human cancer have demonstrated that Apaf-1 or Caspase-9 are commonly reduced in cancer." (PMID 21611191, 2011). "Reduced protein levels of Apaf-1 or Caspase-9 or elevated expression of IAP family members have been found in a variety of cancer cell lines and primary tumor biopsy samples." (PMID 21611191, 2011). "Small molecule inhibitors targeting the DNA-binding interface of Apaf-1 may be used in new cancer therapy by combining them with other drugs, such as BH3-mimetics, to switch tumor cell fates from persistent inflammation to apoptotic cell death." (PMID 39833169, 2025). "This study provides the first evidence that pharmacological concentrations of VC induce the expression of pro-apoptotic proteins such as Apaf-1 and caspases -7 and -9, while inhibiting cancer cell survival proteins like Bcl-2, cyclins D and B1, CDK2, Akt, pI3K, and mTOR." (PMID 40149617, 2025). "Additionally, TUSC2 has previously been shown to interact with two proteins important for regulating cancer progression and apoptosis, c-Abl and Apaf-1, respectively." (PMID 37173921, 2023). "Apaf-1 levels are also decreased in some cancers by microRNAs." (PMID 35281082, 2022). "Recently, apoptotic protease-activating factor 1 (APAF1) in UC has been reported to be the direct target gene of miR-1270, which could induce apoptosis and enhance the cisplatin chemosensitivity of cancer cells." (PMID 36289714, 2022). "A decrease in APAF1 expression may lead to apoptosis reduction, thereby favouring cancer cell survival." (PMID 36142793, 2022). "Similarly, apoptosis protease-activating factor-1 (Apaf1), a key molecule in the apoptotic pathways, is downregulated in different cancer types." (PMID 35223842, 2022). "Thus, the change in the apoptotic roles of APAF1 via alternatively spliced WD40 domain appears to be general mechanisms employed during embryogenesis as well as cancer." (PMID 36509773, 2022). "Cancer cells are widely protected from apoptosis due to low APAF1 levels compared to normal cells." (PMID 35631261, 2022). "They detected the highest value of the expression of anti-apoptosis genes Bcl-2 and livin in cancer cells compared with those co-cultured with T. spiralis E/S proteins and increased expression of pro-apoptosis genes Cyt-C, Apaf-1, caspase-9 and caspase-3 in the treated cancer cells." (PMID 33773560, 2021). "The transfer from cancer-associated adipocytes and ADSC-derived CAFs of exosomal miR-21 could induce paclitaxel resistance through an APAF1- mediated mechanism." (PMID 34440886, 2021). "Cancer-associated adipocytes and fibroblasts secrete exosomal miR-21 that attenuates CDDP-induced apoptosis and promotes CDDP resistance in OVCA cells by targeting APAF1." (PMID 31700155, 2020). "Our results show TH has a potentiating effect on Apaf-1 and Caspase-9 at cancer tissues level." (PMID 28399853, 2017). "MiR-21 in exosomes and tissue lysates isolated from cancer-associated adipocytes (CAAs) and fibroblasts (CAFs) are transferred from CAAs or CAFs to cancer cells, where they suppress ovarian cancer apoptosis and confer chemoresistance by binding to the direct novel target, APAF1." (PMID 29100532, 2017).
cancer (continued). "Validated miR-155 target genes are present in multiple pathways associated with cancer and cancer progression, including EMT (SMAD5), proliferation (SOCS1, INPP5D, and CSF1R), block of differentiation (SPI1, CEBPB), and apoptosis (CASP3, FADD, APAF1, and FOXO3A)." (PMID 27128908, 2016). "Bax/Bcl-2 may have an effect on caspase-3 by enhancing apoptosis of cancer cells by cytochrome c, APAF-1, caspase-9 and other death substrates." (PMID 22266878, 2012). "Zebularine has been shown to be selective towards cancer cells, but is eventually less effective in early stage or less aggressive subtypes to demethylate and subsequently re-express specific, for example tumour suppressor genes such as APAF-1." (PMID 17133271, 2006). "Thus, the inactivation of APAF1 function can lead to drug resistance in cancer cells." (PMID 35550636, 2022). "Furthermore, in a recent study, it has been demonstrated that adipocytes could protect cancer cells by downregulating APAF1, a key protein involved in the formation of apoptosomes." (PMID 28915700, 2017). "However, examination of the apoptosis by electron microscopy and immunostaining of the Apaf-1 and caspase-3 clearly demonstrated that both recombinant and parental strains have induced an identical insignificant level of apoptosis in the A431 carcinoma xenografts." (PMID 25358248, 2014). "Based on the cancer panel, we uncovered that there was up‐regulation in several markers, including GADD45 and CASP9, whilst there was down‐regulation in markers like APAF‐1 and MCM2." (PMID 38938916, 2023). "miR-21 suppresses the expression of APAF1 (apoptotic peptidase activating factor 1) and PDCD4 (programmed cell death 4) to inhibit apoptosis and make cancer cells resistant to chemotherapeutics." (PMID 32204455, 2020). "Mechanistically, HDACi induce an upregulation of cell cycle arrest and pro-apoptotic genes (CDNK1A, APAF1, PUMA, BAK1) and repression of prosurvival genes such as survivin which is in accordance with literature data for different types of cancer." (PMID 31234549, 2019). "It was found that down regulation of APAF1, a putative tumor suppressor gene (TSG), leads to resistance to chemotherapy and disease development in some cancers." (PMID 28875006, 2017). "Other reported targets of miR-24 include proapoptotic (FAF-1, Caspase-9, Bim, and Apaf-1) and cell cycle proteins; miR-24 was also shown to regulate XIAP, reducing the threshold for apoptosis in cancer cells." (PMID 28061479, 2017). "However, in non-cancer cells the ratio of pc-9 to Apaf-1 may be higher." (PMID 27697150, 2016). "Though previous studies indicated that abnormal function of Apaf-1 correlates with loss of sensitivity upon cytotoxic therapy and that upregulation of TCTP is also related to the pathogenesis of chemoresistance in cancer cells, the exact molecular mechanisms and interactions are unknown." (PMID 24606760, 2014).
cancer (continued). "Inclusion of specific Apaf-1 inhibitors in topical and well-localized administrations, but not in systemic ones, to avoid interferences with chemotherapeutics would be of interest to prevent chemotherapeutic-induced unwanted cell death which could improve cancer patient care." (PMID 23437261, 2013). "However, mutations in either Caspase-9 or Apaf-1 have not been commonly identified in cancers." (PMID 21611191, 2011). "Mean expression in carcinoma specimens compared to the control group was measured for MASPIN, PDCD4, GLCCl1, BMPR-II, and APAF-1." (PMID 20331864, 2010). "For example, luteolin prevents cancer via modulation of numerous pathways—inactivates proteins, such as procaspase-9, CDC2, and cyclin B or upregulates caspase-9 and caspase-3, cytochrome C, cyclin A, CDK2, and APAF-1." (PMID 41304998, 2025). "Other microRNAs are reported to regulate Apaf-1 in cancers, but their roles in neurogenesis and myogenesis are not well described." (PMID 35281082, 2022). "Besides the genes encoding ZAPs, we also detected five genes encoding signaling molecules involved in the immune response to cancer, namely TRAF6, EIF2AK2, PIK3CA, APAF1, and POU2F2." (PMID 34844636, 2021). "Interestingly, miR-21 represses the expression of its target’s apoptotic peptidase activating factor 1 (APAF1) and programmed cell death 4 (PDCD4) to inhibit apoptosis and increase paclitaxel resistance in cancer cells." (PMID 32121073, 2020). "In the tumor microenvironment, miR-21 derived from macrophages and CAFs are also transferred to cancer cells via EVs, inducing chemoresistance by activating the phosphoinositol 3-kinase (PI3K)/AKT signaling pathway or binding apoptotic peptidase activating factor 1 (APAF1)." (PMID 29304816, 2018). "miR-21 could repress the expression of its targets apoptotic peptidase activating factor 1 (APAF1) and programmed cell death 4 (PDCD4) to inhibit the apoptosis and confer chemoresistance of cancer cells." (PMID 29228644, 2017). "The mRNA and protein expression of Apaf-1 was increased by treatment with PLCSB, with the greatest Apaf-1 expression observed in the 400-μg/ml PLCSB-treated cells (8.85- and 6.45-fold that of the mRNA and protein expression in the untreated cancer cells, respectively)." (PMID 25624917, 2015). "E2F-1-induced cancer cell apoptosis was accompanied by Bax translocation from the cytosol to mitochondria and the induction of caspase-9 activity, suggesting that E2F-1-induced apoptosis is mediated by PUMA through the cytochrome C/Apaf-1-dependent pathway." (PMID 17263886, 2007). "In addition, HSP decreases Bcl-2, mitochondrial AIF, mitochondrial Apaf-1, and mitochondrial cyt-c, which drive cancer cell apoptosis, while upregulating a few intracellular ROS, ATP, Ca2+, and cytosolic components such as AIF, Apaf-1, cyt-c, caspase-3, caspase-9, and Bax." (PMID 40427522, 2025). "Luteolin prevents cancer via modulation of numerous pathways, that is, by inactivating proteins; such as procaspase‐9, CDC2 and cyclin B or upregulation of caspase‐9 and caspase‐3, cytochrome C, cyclin A, CDK2, and APAF‐1, in turn inducing cell cycle arrest as well as apoptosis." (PMID 39830909, 2025). "Besides this, HSP upregulated some intracellular ROS, ATP, Ca2+ and cytosolic components i,e AIF, Apaf-1, Cyt C, caspase-3, caspase-9, Bax, and down-regulated Bcl-2, mitochondrial AIF, mitochondrial Apaf-1, and mitochondrial Cyt C that mediate apoptosis of cancer cell." (PMID 35128104, 2022).